IL6 (interleukin 6)
Diseases named in the same sentence as IL6 in open-access papers (continued):
Sharing a sentence is not in itself a finding about the gene and the disease.
chronic kidney disease (continued). "Fourth, Inflammation.In patients with chronic kidney disease, an independent negative correlation between inflammatory cytokines (TNF-α, IL-6 and CRP) and FT3 was found." (PMID 37821807, 2023). "On the other hand, it could be argued that in a scenario of chronic renal failure 25(OH)D3 is not efficiently converted to the active form 1α,25(OH)2D3, and patients have been reported displaying normal values of 25(OH)D3 levels (26 ng/mL) and hugely increased IL-6 concentrations (580 pg/mL)." (PMID 34836187, 2021). "Chronic kidney disease (CKD) is a state of chronic, low-grade inflammation which contributes to the accelerated progression of chronic inflammatory disturbances affecting immune balance with increased levels of innate immunity biomarkers, such as C-reactive protein (CRP) and interleukin (IL)-6." (PMID 32290429, 2020). "In addition, elevated levels of inflammatory markers, interleukin-6 (IL-6), tumor necrosis factor-alpha (TNF-α), and C-reactive protein (CRP) in patients with chronic kidney disease (CKD) may induce oxidative stress, thereby accelerating the progression of renal damage." (PMID 38004033, 2023). "Circulating pro-inflammatory cytokines and chemokines such as IL-6, MCP-1 and MIP-1ß are potentially responsible for a hidden form of AKI that may progress toward chronic kidney disease without manifest signs." (PMID 30988316, 2019).
endotoxemia (292 papers, 2007 to 2026). "Here, we show that loss of endothelial expression of the IL-6 pathway inhibitor SOCS3 promoted a type I IFN–like (IFNI-like) gene signature in response to endotoxemia in mouse kidneys and brains." (PMID 40956626, 2025). "Other research has linked worsening heart dysfunction to endotoxemia, which is characterized by elevated levels of endotoxin, IL-6, and CRP." (PMID 41011058, 2025). "In this study, serum TNF-α, IL-1β, and IL-6 levels were remarkably elevated in the alcohol group, indicating that alcohol intake caused enteric-derived endotoxemia and produced large numbers of inflammatory factors." (PMID 37432394, 2023). "The inflammatory cytokines TNF-α, interleukin-1ß (IL1ß) and interleukin-6 (IL6) were strikingly increased in LPS- and HpX-treated animals as compared to untreated controls indicating peripheral inflammation caused by endotoxemia or surgical treatment." (PMID 32557202, 2021). "In mice treated with LPS to cause an endotoxemia and subsequent myocardial injury, administration of Sivelestat prompted a higher survival rate by reduction of pro-inflammatory IL-6 and decreased neutrophil infiltration." (PMID 34869231, 2021). "Our results suggest that LPS caused a significant increase in serum TNF-α and IL-6 levels in the endotoxemia model group, whereas pretreatment with ouabain significantly abolished this phenomenon." (PMID 31182997, 2019). "Weight loss is a hallmark of endotoxemia in both mammals and birds which is mediated through several pro inflammatory cytokines such as IL-1, IL-6, and TNF-α." (PMID 27463239, 2016). "As composition of the diet has been shown to be a critical driver of metabolic endotoxemia, with high saturated fat ingestion causing postprandial endotoxemia with increases in IL-6 even in lean subjects, dietary intervention would be a reasonable initial step." (PMID 37841878, 2023). "Of note, the HDAC inhibitor Cambinol has been shown to inhibit TNF and IL-6 secretion in bone marrow-derived macrophages stimulated with LPS and was associated with greater survival in a murine lethal endotoxemia model and in response to Klebsiella pneumoniae challenge." (PMID 34046027, 2021). "Greater intestinal permeability contributes to endotoxemia, elevated circulating pro-inflammatory factors (e.g., IL-6, TNF-α) and systemic low-grade inflammation." (PMID 41602079, 2026). "In mice with severe endotoxemia, serum interleukin-6 (IL-6) and tumor necrosis factor-α (TNF-α) levels were significantly reduced in DMA-treated animals compared with lipopolysaccharide (LPS)-only controls." (PMID 42001814, 2026). "In sows, APS lowers endotoxemia and gut inflammation (calprotectin), correlating with reduced postpartum IL-6 and reactive oxygen species." (PMID 42294883, 2026). "In a rat endotoxemia model, fluoxetine treatment protected from elevated circulating levels of the pro-inflammatory cytokines tumor necrosis factor–α (TNFα), IL-6, and IL-1β." (PMID 39951524, 2025). "It is well established that IL-6 plays a crucial role in mediating Stat3 activation, and age-related increases in plasma and cardiac IL-6 have been reported during endotoxemia." (PMID 40801652, 2025). "The effects of endotoxemia on the hypoxic mouse brain have been reported to induce exacerbation of inflammatory mediators IL-1β, IL-6, and TNF-α." (PMID 39940901, 2025). "Endotoxemia induces an IL-6 response secondary to toll-like receptor binding, and elevated circulating IL-6 concentrations have been documented in experimentally induced endotoxemia in humans." (PMID 41284707, 2025). "The in vivo efficacy of P12 in LPS‐induced endotoxemia showed a significant reduction in serum IL‐6 and TNF‐α." (PMID 40599085, 2025). "In particular, an intraperitoneal LPS injection in huNSG-QUAD mice resulted in similar serum levels of human TNF, IL-6, IL-8 and IL-1β in an analogous systemic endotoxemia experiment." (PMID 39399507, 2024).
endotoxemia (continued). "In this study, there was a clear increase, over time, in TNF-α, IL-6, and IL-10 in both experimental groups, which is characteristic and consistent with the correct induction of endotoxemia." (PMID 38338117, 2024). "We also analyzed cytokine levels in plasma and detected a strong release of tumor necrosis factor, interleukin-6 (IL-6), monocyte chemoattractant protein-1, and IL-10 48 h after endotoxemia." (PMID 38984201, 2024). "Circulating reactive oxygen species (estimated using a neutrophil oxidative burst assay), glucose, insulin, NEFA, lipoprotein particle profiles, inflammatory markers (glycoprotein acetylation (Glyc-A) and IL-6), and biomarkers of endotoxemia were measured." (PMID 38380649, 2024). "Secondary outcomes included serum lipoprotein particle profiles, neutrophil NADPH oxidase activity, serum inflammatory markers Glyc-A and IL-6, biomarkers of endotoxemia, plasma glucose, and serum insulin and NEFA." (PMID 38380649, 2024). "In adults, intermediate monocytes have been described as the main source of pro-inflammatory IL-6 and IL-8 and as a key subset expanded in endotoxemia." (PMID 36902350, 2023). "Differential regulation of IL-6 and IL-10 responses to splanchnic nerve denervation aligns with our recent findings in rodent endotoxemia." (PMID 37535121, 2023). "MLT also reduces the synthesis of IL-6 and NO during LPS-induced endotoxemia by blocking the NF-κB signaling pathway, thereby blocking its nuclear translocation and DNA binding of the NF-κB p50 subunit and suppressing STAT-1 signaling." (PMID 38203627, 2023). "Serum and peritoneal IL-1β and IL-6 were also reduced by OI treatment of a murine model of lethal endotoxemia and peritonitis." (PMID 38085578, 2023). "↑ Veillonellaceae, endotoxemia, and inflammation (IL-6, TNF-α, IL-2, and IL-13) in cirrhotic patients with HE vs. without HE.↑ Enterobacteriaceae, Alcaligeneceae, and Fusobacteriaceae and ↓ Ruminococcaceae and Lachnospiraceae compared with controls." (PMID 37367929, 2023). "Both EA of the auricular concha and vagus nerve can increase serum TNF-α and IL-6 levels, and downregulate pulmonary NF-κB p65 expression levels in endotoxemia, with similar cholinergic anti-inflammatory mechanisms." (PMID 37753078, 2023). "Endotoxemia increases the production of IL-6 and other cytokines and significantly contributes to a pro-inflammatory state." (PMID 37841878, 2023). "Insulin has anti-inflammatory effects, and the application of insulin can reduce pro-inflammatory mediators, especially TNFα and IL6, in animal models of endotoxemia." (PMID 37063831, 2023). "Methyl palmitate ameliorated histopathological abnormalities and decreased plasma levels of tumor necrosis factor alpha and interleukin 6 in rats with endotoxemia produced by lipopolysaccharide (LPS)." (PMID 37765393, 2023). "It has been found in animal models that clopidogrel can also reduce the levels of pro-inflammatory factors such as TNF-α, IL-6, and chemokines in endotoxemia in brain." (PMID 35659067, 2022). "HSPB5 in combination with methylprednisolone also significantly reduced serum IL-6 levels in endotoxemia mice." (PMID 36510250, 2022). "Monocytes and macrophages produce large amounts of proinflammatory mediators, such as TNF-α and IL-6, and then lead to endotoxemia." (PMID 36532445, 2022). "Our study demonstrates that, in the absence of Gal3, the early LPS-induced peak of circulating TNF-α and IL-6 is significantly attenuated, thus further supporting the deleterious effect of Gal3 under conditions of endotoxemia." (PMID 35163089, 2022). "HSPB5 reduced serum IL-6 levels in both the NZB/W F1 and endotoxemia mouse studies, as well as kidney IL-6 transcript levels in NZB/W F1 mice, possibly by modulating both splenic and peritoneal macrophages given the route of administration." (PMID 36510250, 2022).
endotoxemia (continued). "HSPB5 was also evaluated in combination with methylprednisolone in a lipopolysaccharide-induced endotoxemia mouse model; serum IL-6 levels were measured at 24 h post-endotoxemia induction." (PMID 36510250, 2022). "We quantitated IL-1β, TNF-α, and IL-6 as examples of cytokines which are widely accepted as pro-inflammatory ones in many diseases, including endotoxemia." (PMID 36615318, 2022). "In both CD11c– and CD11c+ microglia during EAE and in microglia during acute LPS-induced endotoxemia, IL-6- and IFN-response genes were highly enriched." (PMID 35429976, 2022). "With the novel peptide KCF18, this study managed to achieve simultaneous inhibitions of TNF-α, IL-1β, and IL-6 and thus can compare the therapeutic effects of triple versus single cytokine inhibitions against endotoxemia." (PMID 35337084, 2022). "Endotoxemia-induced cardiomyopathy was intensified in Park2−/− mice, shown by worsened cardiac contractility and higher production of IL-6." (PMID 35265609, 2022). "Treatment with terrein increased the survival of mice and decreased the production of inflammatory cytokines, including interleukin-1β (IL-1β) and interleukin-6 (IL-6) in an LPS-induced endotoxemia model." (PMID 36422559, 2022). "In summary, the results presented in this report demonstrated that terrein inhibits LPS-induced endotoxemia in mice and decreased levels of IL-1β and IL-6 in serum and lungs were observed in terrein-treated mice." (PMID 36422559, 2022). "Auricular acupuncture and electroacupuncture “Zusanli” (ST36) inhibited the expression of the pro-inflammatory factors TNF-α and IL-6 in rat models of endotoxemia through the cholinergic anti-inflammatory pathway." (PMID 36299906, 2022). "One study found that taVNS inhibited the expression of TNF-α, IL-1β, IL-6, and NF-kB p65 in endotoxemia rat serum through α7nAChR-mediated CAP." (PMID 36299906, 2022). "In patients with endotoxemia, which is followed by increased plasma IL-6 and TNF-alpha levels, plasma YKL-40 increased earlier than serum CRP, which is a nonspecific acute-phase protein synthesized in the liver in response to stimulation, mainly from IL6." (PMID 34579512, 2021). "Increased levels of malondialdehyde (MDA), MIP-2, and IL-6 but decreased production of total antioxidant capacity was observed in mice with endotoxemia subjected to VT = 10 mL/kg compared with the other MV treatment groups and the non-ventilated control mice." (PMID 33567713, 2021). "Vascular endothelial breakdown triggered by upregulated IL-6 and its subsequent binding to IL-6R (i.e., the classical IL-6 signaling) contributes to endotoxemia-induced organ injury." (PMID 34065201, 2021). "Alcohol and corticosterone-induced endotoxemia were accompanied by a synergistic elevation of plasma TNFα, IL-1β, IL-6, and MCP1." (PMID 33436875, 2021). "Endotoxemia increases circulating IL-1, IL-6 and TNF-a, and these cytokines acutely and transiently activate HPA, thus, increase the release of cortisol." (PMID 34493028, 2021). "TET2 functions downstream of the NF-κB signaling pathway by recruiting HDACs to the IL6 promoter resulting in reduced IL6 expression in macrophages and attenuation of inflammatory responses in murine endotoxemia model." (PMID 34394088, 2021). "Microbial imbalance and endotoxemia are able to promote the expression of pro-inflammatory cytokines, such as IL6, TNF-α, IL-1, and plasminogen activator inhibitor-1 in a TLR-4 dependent manner." (PMID 33536239, 2021). "In conclusion, the KCF18 peptide–based simultaneous inhibition of TNF-α, IL-1β, and IL-6 can alleviate liver injury in mice with endotoxemia." (PMID 34065201, 2021). "Specifically, Pro9-3 effectively reduced the serum levels of the inflammatory cytokines TNF-α and IL-6 by 54.5% and 39.4%, respectively, in the LPS-induced endotoxemia mouse model." (PMID 33263333, 2021). "The levels of TNF-α and IL-6 were also inhibited by insulin treatment in a LPS induced murine endotoxemia model." (PMID 33679687, 2020).
endotoxemia (continued). "Increased circulating levels of both endotoxin and IL-6 are signatures of mild inflammation described as metabolic endotoxemia." (PMID 32132660, 2020). "In conclusion, even with elevated endotoxemia, individuals with High VO2max exhibited higher IL-6 concentration in peripheral blood post-acute aerobic exercise and lower IL-10 concentration during recovery (1 h post-exercise)." (PMID 32839476, 2020). "We first found that compared to wild-type mice, Ets2-deficient mice showed higher levels of IL-6 and TNF-α after LPS challenge, indicating the crucial role of Ets2 in attenuating inflammation in mouse endotoxemia." (PMID 31785145, 2019). "MCP-1, TNF-α and IL-6 are potent drivers of immune cell infiltration in mice undergoing endotoxemia." (PMID 31072913, 2019). "It alleviated tumor necrosis factor-α (TNF-α) and interleukin-6 (IL-6) in activated macrophages by downregulating the NF-κB activity, and it reduced the mortality rate in LPS induced endotoxemia mice." (PMID 30297806, 2018). "Hemoadsorption therapy with a clinically approved device (CytoSorbTM) removes cytokines (interleukin-6, interleukin-10, and tumor necrosis factor, amongst others) and improves short-term survival in a rat model of endotoxemia." (PMID 28779451, 2017). "Endotoxemia is known to increase pro-and anti-inflammatory cytokines in mice and human, in particular IL-10, IL-6, and TNF-α34." (PMID 29269852, 2017). "TNF‐α is the main cytokine synthesized during endotoxemia and is considered to be responsible for the expression of IL‐1β, IL‐2 and IL‐6." (PMID 28684640, 2017). "Compared to PMB, which is a known LPS neutralizer, mutant peptide MC1-1 showed an enhanced ability to inhibit TNF-α and IL-6 production and to protect mice with endotoxemia from death at the same concentration." (PMID 28054660, 2017). "Body weight doses from 2.5–7.5 mg/kg of N2 and N6 enhanced the survival rate of peritonitis- and endotoxemia-induced mice; reduced the serum IL-6, IL-1β and TNF-α levels; and protected mice from lipopolysaccharide-induced lung injury." (PMID 28611436, 2017). "As macrophages are major cytokine-producing cells, playing a key role in the response to endotoxemia, we also examined how the hormone affected LPS, IL-6 or TNFα signalling in these cells." (PMID 27484112, 2016). "This dual‐LPS injection model for endotoxemia has been shown previously to result in a pronounced increase in the expression of a number of pro‐inflammatory cytokine genes including IL‐1β, IL‐6, and TNFα." (PMID 25903009, 2015). "The most frequently measured cytokines in studies of low-dose endotoxemia are the pro-inflammatory cytokines IL-6 and TNFα and the anti-inflammatory IL-1 receptor antagonist (IL-1ra)." (PMID 25893426, 2015). "IL-6 is secreted at local sites and released into the blood circulation when homeostatic perturbation occur such as endotoxemia, trauma, endotoxic lung, and acute infections." (PMID 25928408, 2015). "To summarize, chronic low-grade endotoxemia, as seen in the case of T1DM, was associated with decreased levels of LBP and EndoCAb and with elevated levels of TNF-α, IL-6, IL-1β and GM-CSF, indicating chronic inflammation." (PMID 26367738, 2015). "Pawlinski and Mackman proved that genetically modified mice expressing low levels of TF exhibited reduced interleukin-6 expression and increased survival in a mouse model of endotoxemia compared with control mice." (PMID 26025445, 2015). "The preventive administration of fucoidan to mice with endotoxemia resulted in inhibition of increased levels of proinflammatory cytokines (TNFα and IL-6), as well as decreasing of the processes of hypercoagulability." (PMID 24492521, 2014). "A number of studies have demonstrated that cardiac dysfunction during endotoxemia is caused by inflammatory cytokines, including TNF-α, IL-1β and IL-6." (PMID 25209241, 2014).